KRAS (KRas proto-oncogene, GTPase)
Diseases named in the same sentence as KRAS in open-access papers (continued):
Sharing a sentence is not in itself a finding about the gene and the disease.
lung cancer (continued). "In summary, we have uncovered an unexpected role for NOP56 in the surveillance of metabolic ROS in KRAS-mutant lung cancer." (PMID 35039048, 2022). "By upregulating DUSP6, a negative regulator of p-ERK, KRAS mutant lung cancer retrained the ERK1/2 mediated toxicity and promote cell proliferation." (PMID 36619616, 2022). "This holds the promise of concurrent targeting of BCL6 and other KRAS pathway effectors, such as MEK, to treat KRAS-driven lung cancer." (PMID 36377663, 2022). "For example, lung cancer bearing EGFR mutation, and colon cancer bearing KRAS mutation all benefit from inhibitors targeting mutation gene." (PMID 35155577, 2022). "With recent advances in research, direct inhibitors of KRAS gene in lung cancer have been approved for marketing." (PMID 36118526, 2022). "In several preclinical lung cancer mouse models, treatment of KRAS-mutant lung adenocarcinoma (LUAD) with HG106 (a potent System Xc− inhibitor), significantly inhibited tumor growth and prolonged survival." (PMID 36105219, 2022). "Because metastatic NSCLC harboring KRAS G12C can be treated with KRAS‐targeting agents (e.g., sotorasib), the detection of KRAS subtypes using methods such as the Lung Cancer Compact Panel is essential for therapeutic decision‐making." (PMID 35545933, 2022). "In murine models of KRAS-mutant lung cancer, combined MEK and CDK4/6 inhibition trigger innate immune response, especially by NK cells." (PMID 36145516, 2022). "Of note, these early-stage compounds were shown to decrease cell viability and to induce cell apoptosis in KRAS G12C lung cancer cell lines." (PMID 35251972, 2022). "In summary, our findings reveal a crucial role of BCL6 in promoting KRAS-addicted lung cancer and suggest BCL6 as a therapeutic target for the treatment of this intractable disease." (PMID 36377663, 2022). "Our discovery of drug addiction resulting from MEK inhibition has implications for both the treatment of KRAS mutant lung cancers and the continued study of MAPK pathway activation as a potential therapeutic target." (PMID 36418460, 2022). "In the present study, we have uncovered a new and unanticipated mechanism by which NOP56 and mTOR signaling cooperate in metabolic stress response in KRAS-mutant lung cancer." (PMID 35039048, 2022). "In this study, we have characterized how KRASG12C inhibition reverses immunosuppression driven by oncogenic KRAS in a number of preclinical lung cancer models with varying levels of immunogenicity." (PMID 35857848, 2022). "Aurora A interacts with KRAS G12C-CRAF complex in lung cancer cells, and dual inhibition of G12C and aurora A dissociates the complex resulting in a long-term MAPK signaling inhibition and the prevention of tumor relapse." (PMID 35966590, 2022). "Apoptosis-inducing factor (AIF) deletion in KRAS G12D mouse lung cancer has been shown to lead to increased survival by leading to decreased oxidative phosphorylation (OXPHOS) and increased glycolytic activity." (PMID 36230484, 2022). "We previously provided evidence that ACSL3 mediates the activation and retention of extracellularly derived FAs in KRAS mutant lung cancer cells." (PMID 34998392, 2022). "In another study of CRISPR-Cas9 screening, suppression of SHOC, a positive regulator of MAPK signaling, sensitized KRAS-mutant pancreatic and lung cancer cells to MEK inhibitors." (PMID 35372044, 2022). "When MTZ was used in combination with trametinib, a MEK inhibitor, a synergistic cytotoxic effect was observed in KRAS-mutant lung cancer cells." (PMID 36230527, 2022).
lung cancer (continued). "Here, we reported, for the first time, a role for NOP56 in metabolic ROS response in KRAS-mutant lung cancer." (PMID 35039048, 2022). "The expression of GFPT2, an isoenzyme of GFPT1, is specifically induced in KRAS/LKB1 combined mutant lung cancer cells, and promotes tumorigenicity by enhancing glucose influx into HBP." (PMID 36158580, 2022). "This is consistent with our previous findings of the least favorable outcome of lung cancer patients harboring CDKN2A/B loss treated with ICIs in another cohort with both KRAS-mutated and KRAS wildtype patients." (PMID 36230855, 2022). "On the other hand, it can also phosphorylate MAP2K, thereby activating ERK as well as JNK kinases and increasing the KRAS mutant lung cancer cells' viability." (PMID 36439693, 2022). "Using cell line gene expression and KRAS mutation data from lung cancer cell lines, we thus demonstrated the ability of RAS expression signatures to measure oncogenic RAS activity in a lung cancer context." (PMID 36163168, 2022). "The outcome of ISRIB's selective effect on ERO1 KO MDAMB231* breast tumours with up‐regulated PERK pathway is in line with other reports of the effectiveness of ISRIB on mutant KRAS lung cancer with high PERK/p‐eIF2alpha." (PMID 35853086, 2022). "There are three isoforms: KRAS, NRAS, and HRAS, among which KRAS is the one that is implicated in lung cancer oncogenesis." (PMID 36069080, 2022). "Specifically, we identified three lung cancer patients with EML4-ALK, who each also harbored an activating mutation in KRAS, and loss of function mutations in BRCA2 and PTEN, respectively." (PMID 36369474, 2022). "Few reports on the effect of antiangiogenic therapy on KRAS-mutant lung cancer indicated that, compared with chemotherapy, the addition of Bevacizumab seemed to have an adverse treatment response." (PMID 35887766, 2022). "Further research is needed to focus on the efficacy of ICI for Asian patients with lung cancer harboring KRAS alterations." (PMID 35491960, 2022). "Use of the Lung Cancer Compact Panel enabled the detection of KRAS G12D in the wash fluid of a brush cytology sample and thus a diagnosis of pulmonary invasive mucinous adenocarcinoma." (PMID 35545933, 2022). "There were studies showed that mutant KRAS dictates a dependency on synthesized fatty acid to escape ferroptosis, establishing a targetable vulnerability in KRAS-mutant lung cancer." (PMID 36615434, 2022). "Research focused on improving antineoplastic therapies in lung cancer has been based on the genomic and proteomic study of tumors with a known specific genetic basis, such as EGFR and KRAS mutations." (PMID 35565331, 2022). "Studies on lung cancer have shown that deregulated expression or genomic alterations of KRAS oncogenes contribute to tumor progression and metastasis." (PMID 36163484, 2022). "KRAS inhibition mobilizes antitumor immunity in immunogenic lung cancer models through derepressing interferon signaling." (PMID 35857848, 2022). "Their human counterparts, HRAS and KRAS, were discovered in 1982, when human bladder and lung carcinoma cell lines were found to contain DNA sequences homologous to Ha-ras and Ki-ras genes." (PMID 36284306, 2022). "KIMAT1 knockdown suppresses not only KRAS expression but also KRAS downstream signaling, thereby arresting lung cancer growth in vitro and in vivo." (PMID 33795683, 2021). "Because several genes, including DDIT3, TRIB3, and ATF3, were specifically increased due to verteporfin treatment in KRAS-mutant lung cancer cells, we focused on the ER stress pathway." (PMID 33830081, 2021). "For our work, we used a panel of nine human and mouse lung cancer cell lines (sensitive or CTD-resistant) with diverse mutational/oncogenic driver profiles (i.e., KRAS G12 mutants, MET amplification, EGFR exon 19 deletion, among others)." (PMID 33850249, 2021).
lung cancer (continued). "Taking as an example lung adenocarcinoma accounting for the highest proportion of lung cancer, the rate of functional driver gene mutations including EGFR, KRAS and rearrangement of ALK or ROS1, is approximately 60%." (PMID 34814861, 2021). "The increased susceptibility to PERK inhibition was also evident for human lung cancer cells overexpressing KRAS G12C compared to their isogenic cells overexpressing WT KRAS." (PMID 34330898, 2021). "In human bronchial epithelial cells, EMT induced by ZEB1 expression was an early, critical event in the pathogenesis of KRAS mutant lung cancer." (PMID 34680229, 2021). "At the molecular level, mitigating IL-1β signaling would prevent the oncogenic activation of the alternative pathway of NF-κB signaling in lung cancer cells, impairing in this way the cascade initiated by KRAS mutant tumor cells." (PMID 33494181, 2021). "Despite the suggested role of the BLT2 cascade in lung inflammation, little is known about its contribution to the progression of lung cancer, especially KRAS-mutant lung cancer." (PMID 34635780, 2021). "Since the discovery of the involvement of KRAS in lung cancer in 1984 by Barbacid’s group, much effort has been directed at the better characterization of KRAS in the development of lung cancer." (PMID 32948832, 2021). "Collectively, the present study indicates that KRAS-driven lung cancer cells are critically dependent on SOD1 to maintain nucleolar hypertrophy and proliferative capacity." (PMID 33859191, 2021). "In one Lung Cancer Mutation Consortium (LCMC) study, 27% of patients with lung adenocarcinoma had KRAS mutations, and as many as one-third of these patients had another carcinogenic driver." (PMID 34012925, 2021). "Bak is significantly upregulated in tumor tissues isolated from genetically engineered LSL-KRASG12D LKB1fl/fl (KL) mice, further supporting BKA-073, a Bak agonist, as an ideal agent for treatment of KRAS-driven lung cancer." (PMID 34373755, 2021). "We anticipate that these new findings will facilitate the development of strategies against lung cancer, especially KRAS-mutant lung cancer." (PMID 34635780, 2021). "Some studies have shown that CDK4 and cyclin D1 expression is correlated with the presence of KRAS mutation in lung tumors, and a synthetic lethal interaction occurs between KRAS and CDK4 in lung cancer tumor progression." (PMID 34309585, 2021). "Combination of MEK inhibition and PD1/PD-L1 blockade prolonged OS of a KRAS-driven lung cancer model." (PMID 34301278, 2021). "While AMPK reportedly inhibits CPS1 expression in KRAS-mutant lung cancer cells, our results show that it also inhibits CPS1 expression in HCC cells without KRAS mutation." (PMID 33917483, 2021). "Recently, small molecule compounds that covalently bind and modify the most common form of mutant KRAS in lung cancer, KRAS G12C, have shown promise in early clinical trials." (PMID 34068816, 2021). "We found that the KRAS-mutant lung cancer patients showed 2.7-fold increased BLT2 gene amplification compared with the KRAS WT lung cancer patients." (PMID 34635780, 2021). "YAP1 upregulation was further identified as a mediator of resistance to combined TBK1 and MEK inhibition in KRAS mutant lung cancer cells and in a KRAS G12D mutant genetically engineered lung cancer mouse models." (PMID 34685695, 2021). "The combination of a MEK inhibitor with an inhibitor of the antiapoptotic BCL-XL led to increased apoptosis in many KRAS mutant cell lines from different histologies, and tumor regression in in vivo lung cancer mouse models." (PMID 33777798, 2021).
lung cancer (continued). "Despite its remarkable impact on the therapeutic approach in lung cancer, targeting KRAS-mutant lung cancer cells remains a challenge; however, KRAS-G12C–specific inhibitors at the clinical trial stage are forthcoming." (PMID 33830081, 2021). "Initially, the screen was performed and validated on lung cancer cells whose viability depended on KRAS and subsequently, the top-scoring hit, i.e., USP39, was further validated in CRC cells, given that many of them are also dependent on mut-KRAS signaling." (PMID 34065438, 2021). "To examine the effect of BLT2 signaling on nodule progression in KRAS-mutant lung cancer in vivo, we used a transgenic mouse model with a lung-specific expression of mutant KRAS (KrasG12D mice)." (PMID 34635780, 2021). "Many TKIs targeting the MAPK pathway have proved to be ineffective in the treatment of KRAS-driven lung cancers." (PMID 34781949, 2021). "Lack of sustained response to therapeutic agents in patients with KRAS-mutant lung cancer poses a major challenge and arises partly due to intratumor heterogeneity that defines phenotypically distinct tumor subpopulations." (PMID 34309585, 2021). "In summary, our in vitro and in vivo data demonstrate that FGFR1 and PLK1 inhibitors constitute a synergistic drug combination and that the FDA‐approved HCQ further enhances cytotoxicity of the treatment in KRAS‐mutant lung cancer." (PMID 34369083, 2021). "Treatment of KRAS mutant lung cancer remains a clinical challenge, despite the recent approval of the first KRAS targeted inhibitor sotorasib for KRAS G12C mutant NSCLC based on the promising activity in the CodeBreak100 trial." (PMID 35008514, 2021). "KRAS is one of the most prominent oncogenes found in many cancer cell types, predominantly in colon, pancreas and lung cancers." (PMID 33466836, 2021). "KRAS and EGFR mutations are two of the most common drivers of lung cancer that are responsible for approximately 25 and 15% of all NSCLC cases." (PMID 33860729, 2021). "Following this information, EZH2 inhibitors were tested in vivo on KRAS-driven Utx knockout lung cancers and results showed Utx knockout models to be sensitive to EZH2 inhibitors." (PMID 34781949, 2021). "Oncogenic KRAS mutations are a major driver of NSCLC, accounting for over 30% of NSCLC cases in Western countries and 10% of total lung cancer cases in Asia." (PMID 34073318, 2021). "We found that the BLT2 cascade lies downstream of mutant KRAS and contributes to mutant KRAS-driven lung cancer cell proliferation and IL-6 production." (PMID 34635780, 2021). "ISR’s ability to integrate multiple tumor regulatory pathways highlights the potential therapeutic value of its pharmacological inhibition for the treatment of mutant KRAS lung cancer." (PMID 34330898, 2021). "In this study, we analyzed the mutation status of EGFR, KRAS, and PIK3CA in different types of lung cancer patients." (PMID 34217313, 2021). "Collectively, our study unravels a nuclear SOD1 function essential for ribosome biogenesis and proliferation in KRAS-driven lung cancer." (PMID 33859191, 2021). "Our findings demonstrate the tumorigenic function of the PERK/p-eIF2α arm of ISR together with the strong therapeutic benefits of its pharmacological inhibition for the treatment of mutant KRAS lung cancer." (PMID 34330898, 2021). "This was followed by the observation that wild-type KRas can inhibit lung cancer and that wild-type NRas can also suppress its mutant as potently as can KRas." (PMID 34466166, 2021).
lung cancer (continued). "Subtypes of lung cancer were also identified: EGFR mutations were identified with 87% accuracy, MET amplification with 91% accuracy, and KRAS mutations with 90% accuracy." (PMID 34873529, 2021). "In lung cancer, FOSL1 acts as a bridge between KRAS mutations and mitosis and its inhibition will reduce the viability of KRAS mutant cells." (PMID 34430085, 2021). "Conversely, inhibition of GPR87 in lung cancer suppresses tumor proliferation by reducing the expression of KRAS and c-MYC." (PMID 35008182, 2021). "The expression level of BLT2 was highly elevated in KRAS-mutant lung cancer cells and in both mouse and human lung cancers with KrasG12D mutations." (PMID 34635780, 2021). "In KRAS driven lung cancer mouse models mitochondrial metabolism and mitochondrial reactive oxygen species generation, which is allowed by glutamine conversion into α-ketoglutarate, are essential for KRAS induced tumorigenicity." (PMID 33777798, 2021). "The most vulnerable to antiproliferative activity of PRI-2191 was EGFR-mutant HCC827 lung cancer cell line, while KRAS-mutant cell lines were less sensitive." (PMID 33652978, 2021). "In agreement with that, KRAS/STK11 double mutant lung cancers showed worse survival compared to only STK11 mutants: TTP of ~two months vs. five months, and overall survival of ~seven months vs 16 months." (PMID 34164344, 2021). "For lung cancers, in particular, there are high failure rates for mutation evaluation (i.e., 32%, 27%, and 35% for EGFR, KRAS, and ALK tests, respectively) with image-guided percutaneous transthoracic core-needle biopsies." (PMID 34873529, 2021). "Long-term supplementation with the antioxidants N-acetylcysteine and vitamin E promotes KRAS-driven lung cancer metastasis." (PMID 34539975, 2021). "KRAS can also induce fatty acid synthase (FASN) to promote lipogenesis, and inhibition of FASN was shown to block cellular proliferation of KRAS-mutant lung cancer cells." (PMID 34947990, 2021). "Further, the increase of CDA and TYMP expression after treatment with chemotherapy was more pronounced in KRAS mutant lung cancer cells." (PMID 33874986, 2021). "We found that only in both the KRAS-mutant lung cancer cell lines tested, RESV (alone or in combination with PRI-2191) decreased the level of secreted VEGF." (PMID 33652978, 2021). "Despite considerable efforts, therapeutic targeting of mutant KRAS has proven to be very difficult, posing a major challenge to effective lung cancer therapy." (PMID 33859191, 2021). "Low SDPR expression was an independent factor that correlated with shorter overall survival of patients both in lung cancer and KRAS-mutant subgroups." (PMID 33435990, 2021). "We previously reported enhanced blockade of the HER2/HER3 network with F+D by inhibition of ER/HER crosstalk in lung cancer, and we showed that F+D was synergistic in A549 cells, a human KRAS mutant model." (PMID 35008514, 2021). "The first evidence that inhibition of oncogenic KRAS is beneficial from a therapeutic viewpoint came from immunocompetent genetically engineered mouse models (GEMMs) of lung cancer in which lung tumors completely regressed upon genetic removal of mutant KRAS." (PMID 33809660, 2021). "Mutant KRas upregulates de novo lipogenic genes, including FASN, ACC1, and ACLY, in lung cancer and gemcitabine-resistant pancreatic cancer cells, implying that KRAS-mutant cancer cells are more sensitive to inhibitors of FA synthesis." (PMID 33801246, 2021). "We explored prognostic value, expression pattern, and biological function of SDPR in non-small cell lung cancer (NSCLC) and KRAS-mutant lung cancers." (PMID 33435990, 2021). "Collectively, these results suggest that mutant KRAS regulates the expression of the BLT2 cascade in lung cancer cells." (PMID 34635780, 2021).